CD40 (CD40 molecule)
Diseases named in the same sentence as CD40 in open-access papers (continued):
Sharing a sentence is not in itself a finding about the gene and the disease.
Shock (1 paper, 2019). The state in which profound and widespread reduction of effective tissue perfusion leads first to reversible, and then if prolonged, to irreversible cellular injury. "To investigate whether the effect exhibited by LA1 on endotoxic shock was due to inhibition of LPS-induced pro-inflammatory response in macrophages, we first examined the expressions of CD86 and CD40 in macrophages obtained from either LA1 or vehicle-treated mice after LPS treatment." (PMID 30809230, 2019).
squamous intraepithelial lesions (1 paper, 2023). "Therefore, this study aimed to explore the possible impact of CD40 gene polymorphisms on the occurrence of CSCC and high-grade squamous intraepithelial lesions (HSIL) in the northeastern Han Chinese population." (PMID 37691121, 2023). "The three SNPs (rs1800686, rs3765459, and rs4810485) of the CD40 gene were analyzed by multiplex polymerase chain reaction (PCR) combined with next-generation sequencing methods in 421 patients with CSCC, 594 patients with high-grade squamous intraepithelial lesions (HSIL), and 504 healthy females." (PMID 37691121, 2023).
status epilepticus (1 paper, 2021). Status epilepticus is defined as a continuous seizure lasting more than 30 min, or two or more seizures without full recovery of consciousness between any of them. "Since the deficiency of CD40 limited seizure susceptibility, we inquired whether CD40 deficiency was sufficient to mitigate the severity of status epilepticus." (PMID 34446808, 2021).
steatosis (1 paper, 2022). Increased lipid within the cytoplasm of cells. "The plasma levels of CX3CL1, TNF, CD40, CSF‐1, and TWEAK were lower in moderate steatosis versus no steatosis." (PMID 35128832, 2022).
temporal lobe epilepsy (1 paper, 2021). A localization-related (focal) form of epilepsy characterized by recurrent seizures that arise from foci within the temporal lobe, most commonly from its mesial aspect. "Using an immunohistological approach in hippocampal cryosections obtained from patients (n = 4) that underwent neurosurgical treatment for Temporal Lobe Epilepsy (TLE), the CD40 immunoreactivity (IR) was highly expressed in hippocampal regions." (PMID 34446808, 2021).
Thrombocytopenia (1 paper, 2022). A reduction in the number of circulating thrombocytes. "Unlike macrophages, monocytes and platelets that mediate hepatotoxicity, CRS and thrombocytopenia, respectively, cDC1 activation by CD40 agonist do not contribute to any of these dose-limiting toxicities." (PMID 35911742, 2022). "Indeed, preclinical studies demonstrated a safe profile and lack of hepatotoxicity and thrombocytopenia when anti-human CD40 mAb was administered intratumorally." (PMID 35911742, 2022).
thrombotic microangiopathy (1 paper, 2022). The syndromes of microangiopathic hemolytic anemia, thrombocytopenia, and variable signs of organ impairment, due to platelet aggregation in the microcirculation. "Fortunately, the use of anti-CD40 mAb on transgenic pig hearts (GTKOhTg.hCD46.hTBM) blocked the same CD40-CD40 ligand costimulation pathway to avoid thrombotic microangiopathy and allow for the successful survival of pig cardiac xenografts in baboons for 236 days." (PMID 36497122, 2022).
thymic lymphomas (1 paper, 2015). "Furthermore, by gating of the CD11c+ DCs cell population using flow cytometry analysis, we confirmed that the Ia, CD86, CD80, CCR7, CD40 and IL-12 proteins of CD11+ DCs were all down-regulated in thymic lymphomas." (PMID 25923834, 2015).
thymic tumors (1 paper, 2023). "In conclusion, our findings, for the first time, estimated the expression of thymic cortical (β5t, PRSS16, and cathepsin V) and medullary epithelial markers (AIRE, CD40, and claudin-4) in differential diagnosis, Masaoka-Koga stage, histological classification, and prognosis of thymic tumors." (PMID 36797681, 2023).
thyroid tumor (1 paper, 2025). A benign or malignant neoplasm affecting the thyroid gland. "Regarding the expression of CD40 and CD40L in thyroid tissues, a previous study immunohistochemically stained those from 36 PTC and four follicular TC (FTC), demonstrating that most thyroid tumors expressed CD40 and CD40L." (PMID 40150133, 2025).
undifferentiated nasopharyngeal carcinoma (1 paper, 2007). "Engagement of CD40 promotes survival of undifferentiated nasopharyngeal carcinoma (UNPC) cells and similar effects are induced by the EBV oncoprotein LMP-1 that is expressed in a fraction of cases." (PMID 17331231, 2007).
Ureteral obstruction (1 paper, 2019). Obstruction of the flow of urine through the ureter. "We have previously reported that renal CD40 upregulation precedes cellular interstitial infiltrate and fibrosis in the unilateral ureteral obstruction (UUO) model." (PMID 30978213, 2019).
urothelial bladder cancer (1 paper, 2023). "Plasma from muscle-invasive, urothelial bladder cancer patients displayed higher levels of MMP7 (p = 0.028) and CCL23 (p = 0.03) compared to NMIBC patients, whereas urine displayed higher levels of CD27 (p = 0.044) and CD40 (p = 0.04) in the NMIBC group by two-sided Wilcoxon rank-sum tests." (PMID 37391708, 2023).
viral myocarditis (1 paper, 2012). Myocarditis that is caused by an infection with a viral agent. "The highest fold-change (9.24) was observed for the AK235118 (a porcine EST) gene which belongs to the Viral myocarditis pathway, whereas the CD40 (TNF receptor superfamily member 5) was the only down-regulated gene with a fold-change of 1.52." (PMID 22823589, 2012).
vitamin D deficiency (1 paper, 2020). A nutritional condition produced by a deficiency of VITAMIN D in the diet, insufficient production of vitamin D in the skin, inadequate absorption of vitamin D from the diet, or abnormal conversion of vitamin D to its bioactive metabolites. "We found a significant association between vitamin D deficiency and three SNPs of the IL7R gene, namely rs987107 (P-value = 0.047), rs3194051 (P-value = 0.03), and rs1494571 (P-value = 0.036), in addition to two SNPs of CD40, namely rs1883832 and rs6074022 (P-value = 0.049 for both)." (PMID 32111053, 2020).
tumor (1,218 papers, 1998 to 2026). "The activation of CD40 favors a proinflammatory phenotype in tumor-associated macrophages, inducing their killing capabilities and supporting anti-tumor T cell responses." (PMID 40578365, 2025). "In order to explore potential alterations in the expression of surface molecules, eight different extracellular markers associated with tumor immunogenicity, e.g. CD40, were quantified using flow cytometry." (PMID 41345386, 2025). "In the context of cancer, activating CD40 in immune cells associated with tumors can enhance the anti-tumor immune response." (PMID 40003965, 2025). "MDSCs also inhibit the CD40/IL-27 signaling in macrophages, increasing the risk of autoimmune conditions and tumor immunosuppression." (PMID 40872475, 2025). "Strikingly, untreated A375s yield HMDMs exhibiting a tumor-associated macrophage phenotype characterized by CD40, CD80, and CD206 surface expression while injured A375s yield HMDMs with markers of increased antigen presentation, namely HLADR and CD86." (PMID 40539073, 2025). "Although a previous study using a KPC mouse variant reported that anti-CD40 plus Flt3L modestly increased MHC-II levels on tumor-infiltrating DCs,12 we found that this combination resulted in a substantial reduction." (PMID 39178856, 2024). "Conflicting reports have been published regarding CD40 signalling in different cancer cells, with pro‐tumoral effects reported by some, while most have shown an association to increased apoptosis and tumour growth arrest post CD40 stimuli of cancer cells." (PMID 38494863, 2024). "In the MB49 model, it was shown that intravesical treatment with anti-CD40 agonist antibodies caused reduced tumour burden, whereby the therapeutic effect was reduced by blockage of IL-15." (PMID 38630912, 2024). "For example, CD40 is significantly inhibited in tumour-associated macrophages and tumour cells in GIST patients treated with imatinib." (PMID 39070147, 2024). "CD40, which is expressed by both tumor cells and macrophages can cause the release of proinflammatory cytokines as well as CD80 and CD86 thereby resulting in augmentation of ant-tumor functions." (PMID 39003350, 2024). "For instance, IL-6 can induce tumor-associated macrophages supporting tumor development, but IL-6 has also been associated with upregulation of CD40 on these macrophages." (PMID 39065651, 2024). "By IVIS imaging of tumor growth of mice for up to 91 days posttumor, Cxcr3 loss impaired the long-term antitumor activity of αPD-L1 + CD40 agonist." (PMID 36472588, 2023). "Tumor-associated macrophages (TAMs) can adopt antitumoral functions when adequately activated by tumor-specific T cells through interferon-γ (IFN-γ) or CD40 signaling." (PMID 38060331, 2023). "In the context of the tumor microenvironment (TME), ligation of CD40 using agonist antibodies activates tumor associated macrophages (TAMs) to a pro-inflammatory, anti-tumorigenic phenotype that restricts tumor growth." (PMID 39872733, 2023). "CD40, which encodes a key molecule involved in antigen presentation, was also upregulated in the c-Scorehi tumors across tumor types (92%, 23/25)." (PMID 37558751, 2023). "In KitV558Δ/+ mouse GIST model, anti-CD40 antibody activated tumor-associated macrophages (TAMs) to produce TNFα, and enhanced the antitumor activity of imatinib." (PMID 37072770, 2023). "Monocytes (CD14; p = 0.001), conventional dendritic cells (CD11c; p = 0.04), and antigen-presenting cells (CD40; p = 0.01) were all elevated in high TILs, with each being linked to either immunosuppression and/or tumor proliferation." (PMID 37627156, 2023). "When CD40 tumor expression was assessed for association with clinicopathologic features, the only significant finding was that CD40 tumor expression is higher in squamous NSCLC than non-squamous (p = 0.0042)." (PMID 36894898, 2023).
tumor (continued). "The single-gene analysis found that higher CD40 expression in tumours (above median) was associated with longer OS (16.47 versus 9.17 months, P = 0.027)." (PMID 37365284, 2023). "A clinical trial looking at the efficacy of an oncolytic adenoviral vector encoding an anti-CD40 antibody in advanced tumours, alone and in combination with systemic Pembrolizumab, has been completed and is currently awaiting results (NCT03852511)." (PMID 37627206, 2023). "On the contrary, agonistic CD40 antibodies activate macrophages (also highly expressing CD40), causing stroma depletion and tumor regressions." (PMID 38008741, 2023). "Although this population of tumors has a higher expression of CD40, we believe that this association was due to the heterogeneity of cells in the tumor microenvironment and variability of HPV types and their relationship with cells and the microenvironment." (PMID 37970926, 2023). "Genetic ablation of important metabolic enzymes involved in CD40-mediated metabolic reprogramming abolishes agonistic anti-CD40-induced antitumor responses and reeducation of tumor-associated macrophages." (PMID 36823405, 2023). "Flow cytometry revealed that TRIM21 deficiency increased the proportion of CD40+ CD11c+ tumour-infiltrating DCs." (PMID 36797289, 2023). "The CXCL12/CXCR4 axis, together with a variety of other factors, regulated tumor growth and metastasis in OC and the concomitant expression of CD40 and CXCR4 in OC was strongly associated with pelvic metastasis." (PMID 36642706, 2023). "This indicated that within tumor regions, high 4-1BB expression was associated with better survival (Log rank p= 0.04, Cox HR= 0.28), and high CD40 expression resulted in better survival (Log rank p= 0.035, Cox HR= 0.27)." (PMID 37153589, 2023). "Immune checkpoints such as PDCD1LG2, ICOS, CD28, and CD40 were found to be substantially expressed in the high-risk group, indicating that the tumor microenvironment of the high-risk group had a strong immunosuppressive effect." (PMID 36479092, 2022). "The CD40 agonist stimulates antigen-presenting cells to process tumor-associated antigens produced by dying tumor cells, reversing immunosuppressive tumor microenvironments." (PMID 36523993, 2022). "Increase of MDSCs are strongly associated with accumulation of Tregs in the tumor tissues, probably because MDSCs can expand Tregs directly via CD40 expressed on the MDSCs, and also indirectly by recruiting Tregs into the tumor milieu via producing IL17." (PMID 36211375, 2022). "In fact, in mouse models of PDAC, CD40 activation combined with chemotherapy, radiotherapy, or immune checkpoint inhibition has caused tumor regressions, predominantly via T cell activation." (PMID 36077755, 2022). "CD40 agonists potentiate the immunogenicity of DCs, convert TAMs to a tumoricidal phenotype and reverse tumour-associated fibrosis." (PMID 35205769, 2022). "DCs express CD40 which is associated with maturation and an activation phenotype necessary for T cell priming, but also promotes DC survival and an anti-tumor response." (PMID 36230990, 2022). "Evidences suggest that the activation of CD40 is critical in the conversion of “cold tumor” into “hot tumor,” which makes the tumor more susceptible to ICIs." (PMID 35715855, 2022). "Here, in cDC1-deficient hosts, CD40 agonist primed tumor-specific T cells that coexpressed Klrg1 and Lag3, or a Treg marker Foxp3, and these T cells appeared dispensable for tumor control." (PMID 35393950, 2022). "Systemic delivery of a CD40 agonist triggers a rapid cytokine release associated with bone marrow mobilization of myeloid cells and their trafficking into tumor tissues, where they subsequently facilitate the production of MMPs." (PMID 34101617, 2021). "We analyzed the area under the ROC curve (AUC) for CD40 expression in comparison with existing biomarker signatures, including tumor mutational burden (TMB), CD274 (PD-L1) and CD8, as a tool for predicting response to immunotherapy." (PMID 34758832, 2021).
tumor (continued). "These clinical data together support our experimental results showing that IL-6 controls CD40 expression in GBM-associated Mφs, and that IL-6 and CD40 critically regulates tumor immunity and determine pathological outcomes." (PMID 34103524, 2021). "This is important, as CD40 activity drives activation and maturation and its expression is often reduced in tumor-associated dendritic cells." (PMID 33953842, 2021). "Together, these results indicate that inhibition of IDO1, mainly expressed in tumor endothelial cells, reduced expression of immunosuppressive molecules associated with T-cell exhaustion during agonistic CD40 mAb therapy." (PMID 32231867, 2020). "The bioinformatic analysis of differential gene expression in response to agonistic CD40 mAb therapy indicated that enhanced IFN-signaling in the tumor microenvironment underlies the transcriptional response of tumor endothelial cells." (PMID 32231867, 2020). "Another well-established mechanism, which is implicated in priming of tumor-reactive T cells, is engagement of the CD40/CD40L axis." (PMID 33101304, 2020). "In orthotopic PDAC models, anti-CD40 treatment was associated with an increased control of tumor growth." (PMID 35582441, 2020). "IL-2/CD40 induced several age-specific changes on tumor-associated CD11c+ cells including increased TGF-β on elderly DCs." (PMID 30560130, 2018). "Despite its potential synergy with other forms of anticancer therapy, the use of CD40 agonists has also been associated with particular toxicities including cytokine release syndrome, thromboembolic events, and tumor angiogenesis." (PMID 29544515, 2018). "Unexpectedly, IL-2/CD40 promoted a more regulatory phenotype in young tumor-associated CD8+ T cells, on account of increases in several regulatory markers, relative to PBS controls, specifically: CD39, A2AR, A2BR, ICOS, LAG-3, and PD-1." (PMID 30560130, 2018). "Macrophages from elderly mice impaired anti-tumor T cell function and was associated with poorer responses to IL-2/anti-CD40 immunotherapy." (PMID 30459812, 2018). "The only common effect of IL-2/CD40 on tumor-associated CD11c+ cells seen in both age groups was up-regulation of IFN-γ." (PMID 30560130, 2018). "CD40-deficient mice exhibit an impaired tumor growth and an atrophied tumor vasculature in the mammary glands." (PMID 30305116, 2018). "In agreement, tumor associated DCs presented higher levels of maturation markers (CD40, CD80 and MHC-I and II molecules) after RT, yet if treatment was performed in an Ifnar1 KO background, therapeutic control was completely lost." (PMID 29050360, 2017). "Most notably, these costimulatory agents have been combined with tumor cell lysate and tumor-associated peptide vaccine platforms supplemented with anti-CD40 mAbs and TLR ligands that enhance antigen presentation by DCs." (PMID 29207606, 2017). "Here, we describe enhanced anti-tumor efficacy of an in vivo electroporation-delivered DNA vaccine by inclusion of a genetically encoded chimeric MyD88/CD40 (MC) adjuvant, which integrates both innate and adaptive immune signaling pathways." (PMID 27741278, 2016). "In GEM models, CD40 antibodies caused tumor regression by inducing macrophage infiltration into the tumors and degradation of tumor-associated stroma." (PMID 26266422, 2015). "During tumor progression, CD40 levels decreased, and this decrease was associated with an increased number of MDSC in the tumor." (PMID 26462153, 2015). "CD40 mutant (CAC → CAA, 78His → 78Gln, NCBI Assay ID: ss23134804, Reference SNP ID: rs17177493) is a variant type of CD40 found on the surface of the U266 cell line and in freshly isolated tumor cells." (PMID 24885116, 2014). "A strategy proposed to overcome stromal desmoplasia is depletion of tumor-associated fibroblasts by using CD40 agonists." (PMID 23641216, 2013). "A major advantage using the adapter-based CD40-targeting approach is flexibility to use different sets of Ad vectors expressing unique tumor associated antigens." (PMID 23056548, 2012).